BRCA1 (BRCA1 DNA repair associated)
Diseases named in the same sentence as BRCA1 in open-access papers (continued):
Sharing a sentence is not in itself a finding about the gene and the disease.
ovarian carcinoma (continued). "Olaparib is a novel PARP inhibitor with increased specificity for PARP-1 and -224 that was approved for the treatment of ovarian cancer positive for BRCA1/2 mutations (FDA reference ID: 3675412) in 2014." (PMID 28004814, 2016). "Studies from human patients with increased risk (mainly with germ line mutations in the BRCA1/2 genes) to ovarian cancer have provided evidence for the fallopian tube epithelium being one of the sites of origin for SOC." (PMID 27588493, 2016). "Family history of breast and/or ovarian cancer is enriched in patients with BRCA1/2 pathogenic variants but less predictive for non-BRCA1/2 related pathogenic variations." (PMID 29263802, 2016). "As mentioned in the 2th patient who carried the cancer-predisposing mutation in BRCA1, she died from breast and ovarian cancer in her later 50’s." (PMID 27930734, 2016). "In this study, all cases were classified as serous cancers which is the most frequent histological subtype of ovarian carcinomas and has the highest incidence of BRCA1/2 mutations 7, 22 of all ovarian tumors." (PMID 27167707, 2016). "Treatment outcomes appear to be better for ovarian cancer (OC) patients carrying the BRCA1/2 germline mutation than for patients with sporadic OC." (PMID 26807161, 2016). "Based on these findings, the European Medicines Agency (EMA) included both germline and somatic BRCA1/2 mutation patients with ovarian cancer for olaparib maintenance monotherapy." (PMID 27257965, 2016). "Women who are carriers of BRCA1 mutations present with a 39–46 % lifetime risk of developing ovarian cancer, and for carriers of BRCA2 mutations the lifetime risk is 12–20 %." (PMID 27468354, 2016). "In particular, only 8 (24.2% (8/33)) non-BRCA1/2 gene mutation carriers had a family history of breast or ovarian cancer." (PMID 29263802, 2016). "BRCA1/2 mutations are present in 5%–15% of all breast and ovarian cancers and have been found in other hereditary diseases, in the absence of homolous recombination, cells are more vulnerable to genomic instability." (PMID 27213343, 2016). "The majority of BRCA1/2 associated ovarian cancers present as high-grade serous histology in advanced stage." (PMID 27463617, 2016). "The aim of this study was to evaluate three intragenic BRCA1 marker polymorphisms in families, which have two or more patients with breast/ovarian cancer in comparison to healthy women." (PMID 27351029, 2016). "The aim of our study was to assess clinical features and treatment outcomes in ovarian cancer patients, having a founder mutation in BRCA1 gene in comparison with clinical results of sporadic ovarian cancer patients." (PMID 26753012, 2016). "Olaparib, a PARP1 inhibitor, is now approved for patients with advanced ovarian cancer harboring BRCA1 or BRCA2 deleterious mutations, as loss of BRCA sensitizes these tumors to further inhibition of DNA repair and results in a synthetic lethality." (PMID 27004405, 2016). "Pathogenic mutations in BRCA genes were found in 13 of the 47 (28%) ovarian cancers: eight were in BRCA1 and five in BRCA2." (PMID 26745875, 2016). "The analysis of BRCA1/2 somatic mutations is crucial for guiding therapeutic decisions in ovarian cancer." (PMID 27907908, 2016). "Currently, patients are being stratified for PARP inhibitor treatment by germline BRCA1/2 mutation status, which comprise 10–15% of ovarian cancer patients." (PMID 25868852, 2015). "This, combined with anexpanding range of clinical implications for ovarian cancer patients found to carrya BRCA1 or BRCA2 mutation, has presented a central role forgenetic testing." (PMID 26669451, 2015).
ovarian carcinoma (continued). "In conclusion, we propose routine genetic screening for at least five recurrent BRCA1 mutations (c.5266dup, c.181T>G, c.3700_3704del, c.68_69delAG, c.4034delA) in all ovarian cancer patients in the Polish population." (PMID 25366421, 2015). "For example, germline mutations in BRCA1 or BRCA2 are associated with ovarian cancer at a rate of only 20–40%, suggesting the presence of other unidentified mutations in other genes as an etiology." (PMID 26301412, 2015). "Germ-line mutations in BRCA1/2 genes account for most of the hereditary breast and/or ovarian cancers." (PMID 26061043, 2015). "Inherited mutations in breast cancer susceptibility gene 1 (Brca1), a well-known tumour suppressor implicated in familial breast and ovarian cancers, is one of the best defined risk factor for development of breast and ovarian cancer." (PMID 26227626, 2015). "An NGS 25-gene panel revealed that the frequency of mutations in genes other than BRCA1/2 is 4.3%, of which 3.9% are in genes associated with breast/ovarian cancer." (PMID 25948282, 2015). "The Association of Gynecologic Oncology recommends that testing for a germline mutation in BRCA1 or BRCA2 should be offered to all patients with epithelial ovarian cancer." (PMID 26109557, 2015). "Approximately 15 % of the patients with epithelial ovarian cancer have a germline mutation in the BRCA1 or BRCA2 genes." (PMID 26109557, 2015). "Germline mutations of the breast cancer susceptibility gene 1 (BRCA1) significantly increase the risk of developing breast and ovarian cancers." (PMID 25699710, 2015). "Recent findings, however, have shown that up to 15 % of patients with epithelial ovarian cancer have germline mutations in BRCA1 or BRCA2." (PMID 26109557, 2015). "In one meta-analysis, cumulative breast and ovarian cancer risks for BRCA1 mutation carriers are 57 and 40%, respectively, while, for carriers of BRCA2 mutations, these risks are 49 and 18%, respectively." (PMID 25869442, 2015). "The decisions about who should undertake testing for germline BRCA1 andBRCA2 mutations, as well as when and how it should be carried out, arebecoming increasingly important for ovarian cancer patients in the UK." (PMID 26669451, 2015). "Albeit both studies confirmed the strong founder effect for BRCA1 5266dup and c.181T>G alterations, the latter reported other recurrent BRCA1/2 mutations in the group of Polish patients with ovarian cancer." (PMID 25366421, 2015). "In BRCA1/2 germline mutation carriers, approximately 65 % of all ovarian carcinomas are of the serous subtype." (PMID 26286255, 2015). "A previous study of French Canadian women with ovarian cancer was limited by both sample size investigated, and by spectrum of BRCA1 and BRCA2 mutations screened, where additional mutations have since been identified and found to recur in this population." (PMID 25884701, 2015). "Familial history remains the strongest risk factor for developing ovarian cancer (OC) and is associated with germline BRCA1 mutations, such as the 185delAG founder mutation." (PMID 26357657, 2015). "Ovarian carcinoma occurs at younger age in BRCA1 mutation carriers than in BRCA2 mutation carriers or the general population (both mean and median 51 versus 56 versus 60 years respectively)." (PMID 26286255, 2015). "This encompasses BRCA1/2 mutation carriers and women with familial susceptibility to ovarian cancer, which is determined by having a pedigree-based estimated lifetime risk of ≥10 %." (PMID 26264902, 2015). "The BRCA-PARP combination is the first successful example of a SL relationship that has seen clinical applicability in breast and ovarian cancers, to kill cancer cells deficient in BRCA1/2 (cells with ‘BRCAness’ property)." (PMID 26427375, 2015). "Limited significance of age at diagnosis as well as patient’s family history justifies genetic screening for the founder BRCA1/2 mutations in all ovarian cancer patients." (PMID 25366421, 2015).
ovarian carcinoma (continued). "Germline mutations in these genes represent significant risk factors for developing HGSOC: for a woman with a BRCA1 mutation, the risk of developing epithelial ovarian cancer is 39–46%, and with a BRCA2 mutation, 12–20%." (PMID 26579492, 2015). "The percentage of BRCA1/2 mutations in unselected ovarian cancer patients identified in the current study is comparable to that previously reported (14.9 vs 13.5 and 13.9 %)." (PMID 25366421, 2015). "When BRCA1/2 mutations were discovered it was extensively reported that these mutations played a role in the development of breast and ovarian cancer." (PMID 26236408, 2015). "Recent work has suggested a role for BRCA1/2 and defective HR in sporadic ovarian cancer resulting from somatic mutations or epigenetic mechanisms." (PMID 26510816, 2015). "The analyses showed also the importance of ATP7B gene in ovarian carcinogenesis, both studied variants of which significantly modulated the ovarian cancer risk in all groups excluding the group with BRCA1 mutation." (PMID 25591549, 2015). "Germline and somatic mutations in BRCA2 (and BRCA1) have been associated with survival in two ovarian cancer studies." (PMID 25950620, 2015). "To validate usefulness of targeted assays in screening for BRCA1/2 mutations, we performed a next generation sequencing in the group of 134 patients with unselected ovarian cancer." (PMID 25366421, 2015). "Based on a series of basic, preclinical and clinical studies, the Poly (ADP-ribose) Polymerase 1 (PARP1) inhibitor, olaparib, has recently been approved for use in ovarian cancer patients with BRCA1 or BRCA2 mutations." (PMID 25883215, 2015). "The 317 ovarian cancer patients were divided into three groups: the BRCA1/2 alteration carriers group, the miRNA-related high-risk group and the miRNA-related low-risk group." (PMID 25537514, 2015). "Lifetime risk for ovarian cancers is 40–66 % and 10–20 % in BRCA1 and BRCA2 germline mutation carriers, respectively, in contrast to 1.8 % in the general population." (PMID 26337050, 2015). "In analogy, responses of ovarian cancer lines to cisplatin were also influenced by their BRCA1/2 mutation status as well as the status of related HR genes." (PMID 25852742, 2015). "At least 5 of the 17 known FA genes, D1/BRCA2, J/BRIP1, N/PALB2, O/RAD51C and S/BRCA1, are well-established breast and/or ovarian cancer susceptibility genes." (PMID 26085575, 2015). "Subsequently, mutations in BRCA1 were confirmed in families with early onset breast and ovarian cancer." (PMID 25869442, 2015). "One of the twelve samples (AZ68) was an ovarian cancer sample where the pathogenic mutation BRCA1 c.1105delG p.(Asp369MetfsTer5) had been identified and confirmed." (PMID 25859162, 2015). "The deregulation of the three miRNAs (hsa-miR-545, hsa-miR-146a and hsa-miR-148a) was significantly associated with favorable OS and PFS in wild-type BRCA1/2 ovarian cancer patients." (PMID 25537514, 2015). "Over the years research has highlighted the link between mutations in BRCA1/2 genes and susceptibility to breast and ovarian cancer." (PMID 26236408, 2015). "The worldwide prevalence of BRCA1/2 mutations in consecutive ovarian cancer series is estimated at 5 to 15 % and varies markedly depending on the population’s ethnic background." (PMID 25366421, 2015). "In 2000, three founder alleles of BRCA1 (c.5266dup, c.181T>G, c.4034delA) were reported in Polish families with a strong aggregation of breast or ovarian cancers and subsequently incorporated into the standard genetic screening panel." (PMID 25366421, 2015). "The problems associated with a requirement for very high sensitivity can be to some extent overcome by targeting the screening test to at-risk populations with higher prevalence of the cancer, e.g., BRCA1/2 mutation carriers for ovarian cancer screening." (PMID 25988180, 2015). "The inheritable predisposition of the BRCA1/2 genes for breast and ovarian cancers has been well established and widely researched." (PMID 26236408, 2015).
ovarian carcinoma (continued). "Defect of BRCA1/2 is involved in the development of ovarian carcinomas and defects in BRCA1/2 are associated with the resistance to platinum-based chemotherapy in ovarian carcinomas." (PMID 25823848, 2015). "Women at high-risk for ovarian cancer (those with BRCA1 and BRCA1 mutations) are strongly advised to have prophylactic RRBSO once child-bearing is complete based on the good short term data indicating the improvement in mortality in this cohort." (PMID 27231565, 2015). "Human cancers with underlying defects in HDR (such as BRCA1 inactivated breast and ovarian cancers) show sensitivity to poly (ADP-ribose) polymerase 1 (PARP) inhibition." (PMID 26374986, 2015). "PARP functions in the base excision repair (BER) pathway to repair SSBs, and inhibitors have been found to stabilize or regress ovarian cancer with BRCA1/BRCA2 mutations." (PMID 26579492, 2015). "Inherited mutations in BRCA1 are well known to confer an increased lifetime risk of developing breast or ovarian cancer." (PMID 26092435, 2015). "BRCA1 is a major breast and ovarian cancer susceptibility gene that maintains genomic stability by regulating DNA repair/recombination and controls cell cycle progression." (PMID 25762631, 2015). "Germline mutations in breast cancer susceptibility gene 1 (BRCA1) increase the risk of breast and ovarian cancers." (PMID 25880076, 2015). "The purpose of the study was to establish the frequency of germline BRCA1/2 mutations in a group of 134 unrelated patients with primary ovarian cancer." (PMID 25366421, 2015). "Historically,germline BRCA1/2 mutations were thought to be associated withapproximately 10% of all ovarian cancers, but this is now known to bean underestimate." (PMID 26669452, 2015). "Mutations in the breast cancer susceptibility 1 (BRCA1) gene are catalysts for breast and ovarian cancers." (PMID 26320175, 2015). "This analysis was done for the group of sporadic ovarian cancer patients (BRCA1-) to avoid the strong influence of mutated BRCA1 gene." (PMID 25591549, 2015). "It has been established that a woman’s risk of developing breast or ovarian cancer is greatly increased if she carries a mutated BRCA1/2 gene." (PMID 26236408, 2015). "In the group of 134 patients with unselected primary ovarian cancer, pathogenic BRCA1 or BRCA2 mutations were found in 20 individuals (14.9 %)." (PMID 25366421, 2015). "Hereditary breast and ovarian cancer is an inherited genetic condition associated with a mutation in the BRCA1 or BRCA2 gene." (PMID 26557407, 2015). "Overall, sequencing of BRCA1/2 coding exons identified additional predicted cancer risk mutations in 52 out of 512 (10%) patients with familial and/or an early onset breast/ovarian cancer that were missed using our standard genotyping procedure." (PMID 25948282, 2015). "Across cancer types, a higher percentage of breast and ovarian cancer cases were identified as having rare truncation variants in cancer genes versus other cancer types, due predominantly to high frequencies in BRCA1/2." (PMID 26689913, 2015). "The identification of LRGs in breast and/or ovarian cancer families has widened the mutational spectrum of the BRCA1 gene, increasing the number of patients who can benefit from molecular screening." (PMID 25814778, 2015). "In line with the recommendations of the American Society of Clinical Oncology testing for recurrent BRCA1 mutations is required in each case of ovarian cancer in the Polish population (1996)." (PMID 25366421, 2015). "The most promising strategy for treating HR-deficient tumors, such as BRCA1-mutated breast and ovarian cancers, is the use of PARP inhibitors." (PMID 27462418, 2015). "Several studies reported that germline mutations in BRCA1 gene increase the risk to develop breast and ovarian cancers." (PMID 25880076, 2015). "The aim of this study was to establish the frequency of germline BRCA1/2 mutations in consecutive ovarian cancer series from northern Poland." (PMID 25366421, 2015).
ovarian carcinoma (continued). "Oral Contraceptives: The use of oral contraceptives has demonstrated a reduction in the risk of ovarian cancer by up to 45% to 50% in BRCA1-mutation carriers and up to 60% in BRCA2-mutation carriers." (PMID 26557407, 2015). "Uptake was higher in BRCA1/2 mutation carriers than in women with familial susceptibility to ovarian cancer (90.6 and 78.0 % respectively)." (PMID 26264902, 2015). "Presently, genetic risk evaluation for ovarian cancer can be conducted for subjects with a family history of some cancer and/or BRCA1/2 mutations identified within families." (PMID 25173882, 2015). "Chromatin immunoprecipitation analysis indicated that the levels of H3K9ac and ETS1 factors were significantly increased in BRCA1-mutated ovarian cancer tissue (Fig. 2Ai and Aii)." (PMID 24448423, 2014). "Their study examined content analysis of print news, specifically looking at the tone of discussions and how journalists reported on BRCA1/2 mutations and testing as well as hereditary breast and ovarian cancer." (PMID 25032040, 2014). "Although only 5–10% of ovarian cancers are directly attributable to a germline mutation in BRCA1 or 2, there is a growing body of evidence to suggest that additional mechanisms of BRCA dysfunction are involved in the pathogenesis of ovarian cancer." (PMID 24579064, 2014). "Univariate survival analysis demonstrated an association between the hypomethylated ETS1 motif and an increased risk of death in BRCA1-mutated ovarian cancer patients." (PMID 24448423, 2014). "Detecting mutation in BRCA1/2 is a generally accepted strategy for screening ovarian cancers that have impaired homologous recombination (HR) ability and improved sensitivity to PARP inhibitor." (PMID 25437005, 2014). "A notable mouse model of restricted BRCA1 deletion in granulose cells was produced to investigate the association between menstrual cycle and ovarian cancer risk." (PMID 24616881, 2014). "Germline inactivating variants in BRCA1 lead to a significantly increased risk of breast and ovarian cancers in carriers." (PMID 24845084, 2014). "Of particular interest and potential clinical relevance, the relationship between BRCA1 and GR expression was studied in 40 non-BRCA1-mutated ovarian cancer specimens." (PMID 24629067, 2014). "This is an interesting result, given that to date only one SNP, rs4691139 in the 4q35.3 region, also identified through the iCOGS effort, has been found to modify ovarian cancer risk specifically in BRCA1 carriers." (PMID 24698998, 2014). "Much of the current research surrounds the use of PARP inhibitors as effective mono-therapy for breast and ovarian cancers with BRCA1 and BRCA2 mutations." (PMID 25369795, 2014). "Yet when Angelina Jolie came out with the very frank story of her potential risk for breast and ovarian cancer due to her BRCA1 mutation status, it really got me thinking." (PMID 25032040, 2014). "In humans, BRCA1/2 mutations are strongly associated with increased risk for malignancies, including breast and ovarian cancers." (PMID 25036526, 2014). "Approximately 10% of the epithelial ovarian cancers (EOC) are caused by mutations in the tumor suppressor gene BRCA1." (PMID 25594072, 2014). "Our first example relates to the widely-expressed tumor suppressor BRCA1 that causes predisposition to hereditary breast and ovarian cancer." (PMID 24921629, 2014). "It is, however, interesting to note that BRCA1-mutated ovarian cancer tissue showed dramatically reduced the expression of GR compared to adjacent normal tissue." (PMID 24629067, 2014). "This approach has been an important step toward individualization of therapy for germline BRCA1/2 mutation (gBRCAm)-associated breast and ovarian cancers." (PMID 24616882, 2014).